GPT2 (glutamic--pyruvic transaminase 2)
Diseases named in the same sentence as GPT2 in open-access papers (continued):
Sharing a sentence is not in itself a finding about the gene and the disease.
tumor (continued). "Consistently, all the six DEGs (GLS2, ASS1, FOLH1B, AGXT2, CPS1, and GPT2) enriched in “arginine biosynthesis” in our results were significantly downregulated in tumor hepatic tissue from HBV-infected patients compared with adjacent nontumor tissues." (PMID 32775402, 2020). "We hypothesize that high tumor GPT2 expression contributes to a glutamine-depleted TME, which primarily inhibits the function and infiltration of activated immune cells (leading to a lower overall immune score), while having a lesser impact on naïve cells." (PMID 41323791, 2025). "The results revealed a significant positive correlation between GPT2 expression and tumor stemness." (PMID 41323791, 2025). "All in all, GPT2 is a pivotal enzyme converting glutamine-derived glutamate into α-ketoglutarate (α-KG), had not been systematically investigated in BCa, despite its documented role in promoting tumor growth and anabolic metabolism in other malignancies." (PMID 41323791, 2025). "Notably, GPT2 expression was negatively correlated with immune, stromal, and combined scores, but positively correlated with tumor purity in BCa." (PMID 41323791, 2025). "GPT2 and SLC1A5 inhibitors may inhibit tumour growth and distant metastasis, and increase susceptibility to 5-fu and L-OHP therapy." (PMID 37829798, 2023). "This further explains the effect of GPT2 on tumour growth and metastasis." (PMID 37829798, 2023). "Nevertheless, these findings indicate that GPT2 promotes tumor growth in mice." (PMID 36010673, 2022). "GPT2 KD in U87MG cells significantly decreased primary tumor growth in mice as compared with SC." (PMID 36010673, 2022). "Whether GPT1 has the similar function in regulating energy metabolism and tumor proliferation like GPT2 needs in-depth investigation." (PMID 35804447, 2022). "Furthermore, GPT2 is found to be in 18 (FDR adjusted p-value < 0.05 and correlation difference > 0.5) other tumor-specific gene-metabolite associations." (PMID 29506475, 2018). "Together, these data suggest that upregulation of GPT2 by PIK3CA mutations produces more α-KG from glutamine to replenish the TCA, thereby generating more ATP and intermediates for macromolecule synthesis to sustain rapid growth of PIK3CA mutant tumours." (PMID 27321283, 2016). "Although AOA is a pan-aminotransferase inhibitor, our data clearly demonstrate that the tumour inhibitory effect of AOA on PIK3CA mutant xenografts is indeed on-target to GPT2, because GPT2 knockdown cells grow much slower in nude nice and these tumours are insensitive to AOA treatment." (PMID 27321283, 2016). "Furthermore, GPT2 cooperates with glutamine transporters to promote tumour metastasis." (PMID 37829798, 2023). "GPT2 knockdown reduced EMT and stemness in BCa cells, suppressed their proliferation, invasion, and migration, and inhibited subcutaneous tumor formation and growth in nude mice." (PMID 41323791, 2025). "SRCC increase glutamine uptake and metabolism by upregulating GPT2 and SLC1A5, leading to tumour resistance and malignant progression." (PMID 37829798, 2023). "However, the role of GPT2 in tumor metastasis remains unclear." (PMID 36923530, 2023). "Genetic inhibition of GPT2 decreases GBM cell growth and migration in vitro and tumor growth in mice." (PMID 36010673, 2022). "Among these ten genes, the expression levels of SETD1B, ACSF2, MUC1, KLHL24, PML, MT1G, and GPT2 were higher in tumor tissues than those in normal tissues, while HIC1, AKR1C1, and LOC390705 were lower expressed in tumor tissues." (PMID 35071242, 2021). "Additionally, using the ESTIMATE algorithm, we assessed the relationship between GPT2 expression and TME components in BCa, including tumor purity, immune score, stromal score, and combined scores." (PMID 41323791, 2025). "Particularly in GBM, the accumulation of Glu due to GPT2 and GLUD1 downregulation correlated to upregulation of genes related to GSH synthesis which could favor tumor cell survival, mostly in the most aggressive MS subtype." (PMID 33910646, 2021).
tumor (continued). "Although the current data strongly support that GPT2 promotes tumor metastasis through the GABA-increased calcium influx, we could not entirely exclude the other possibility for GPT2-induced tumor metastasis since GPT2 regulates the α-KG generation." (PMID 36923530, 2023).
cancer (24 papers, 2014 to 2025). A tumor composed of atypical neoplastic, often pleomorphic cells that invade other tissues. "To understand whether SDH loss imposes dependency on GPT2 for proliferation in cells of human origin, we leveraged genome-scale pooled drop-out shRNA screening data for 285 genomically characterized human cancer cell lines from Project Achilles." (PMID 37414778, 2023). "Analysis of Cancer Cell Line Encyclopedia (CCLE) datasets showed widespread GPT2 overexpression across numerous cancer cell lines." (PMID 41323791, 2025). "In our study, GPT2 knockdown reduced the proportion of BCa stem cell subsets, suppressed cancer cell proliferation, and downregulated the CSC markers (ALDH1A1, SOX2, OCT4, and KMT1A)." (PMID 41323791, 2025). "Pan-cancer analysis further demonstrated significantly higher GPT2 expression in 26 cancer types, including BCa, than in adjacent normal tissues, and its overexpression was correlated with poor prognosis in BCa." (PMID 41323791, 2025). "Using the cBioPortal database, we explored the correlation between GPT2 expression and promoter methylation in 33 cancer types." (PMID 41323791, 2025). "For each cell line, averaged sensitivity profiles to shRNAs targeting GPT or GPT2 were correlated to SDHB expression data from the Cancer Cell Line Encyclopedia (CCLE)." (PMID 37414778, 2023). "The combination of BPTES with the GPT2 inhibitor cycloserine shows synthetic lethality in multiple cancer cell lines." (PMID 35831624, 2022). "Given the roles of GDH, GOT2, and GPT2 in cancer cells, further efforts should be invested to develop specific and potent inhibitors for these enzymes." (PMID 35831624, 2022). "For instance, a recent study has shown that GLS1 inhibition induces an increase in mitochondrial glutamate-pyruvate transaminase 2 (GPT2) to assist in TCA cycle anaplerosis for sustaining cancer cell growth and survival." (PMID 32943735, 2020). "GPT2 has been widely suggested to be a critical determinant for the tumorigenesis of different cancers." (PMID 32660149, 2020). "It is well established that GPT2 plays a key role in the development of cancer." (PMID 38459004, 2024). "Moreover, several inhibitors of GOT1 and GPT2, likely Hydralazine hydrochloride, Aspulvinone O, Oxamate and Aminooxyacetate, were reported to reduce growth in different cancer lines." (PMID 37445598, 2023). "Additionally, pharmacological inhibition of OGT increases the expression of alanine aminotransferase 2 (GPT2), which can be targeted to reduce cancer cell survival and proliferation." (PMID 37838167, 2023). "Whether GPT1 also possesses a cancer-promoting function, like GPT2, in regulating energy metabolism and supporting cancer cell growth is yet to be determined." (PMID 32660149, 2020). "Finally, beside the skeletal muscle, the TH-GPT2-anaplerosis axis could be part of the pro-glycolitic and pro-Warburg effects exerted by TH and GPT2 in cancer, in which anaplerosis is a keystone of the metabolic reprogramming of cancer cells." (PMID 35196498, 2022). "In BCa, our data suggest GPT2 primarily drives EMT and stemness via glutamine-derived α-KG accumulation, which differentially modulates HIF-1α/Wnt pathways compared to other cancers." (PMID 41323791, 2025). "However, the specific mechanism by which GPT2 regulates ferroptosis in cancer remains unclear." (PMID 38459004, 2024). "In cancer cells, conversion of Glut into α-ketoglutarate (α-KG) relies on glutamate dehydrogenase (GLUD1), glutamic-pyruvic transaminase 2 (GPT2) or glutamic-oxaloacetic transaminase 2 (GOT2)." (PMID 38424041, 2024). "Consistently, GPT2 KO decreased the expression of ITGA6, a HIF-induced integrin family member involved in cancer cell motility, in U251MG cells under 20% and 1% O2." (PMID 36010673, 2022). "Our results revealed a strong negative correlation between GPT2 expression and DNA methylation in 31 cancer types, including BCa, suggesting that GPT2 overexpression in BCa stems from promoter hypomethylation." (PMID 41323791, 2025).
cancer (continued). "Remarkably, IGF2BP2 governs glutamine uptake and metabolism by upregulating MYC, glutamic-pyruvic transaminase 2 (GPT2), and solute carrier family 1 member 5 (SLC1A5) in AML, which indicates that IGF2BPs could regulate amino acid metabolism in cancers." (PMID 37554271, 2023). "Unlike mitochondrial GPT2, which has been extensively studied in cancer, GPT1 has been rarely reported in cancer." (PMID 37851339, 2023). "Therefore, the inhibition of glutamine uptake by the glutamine transporter (ASCT2), as well as the inhibition of glutaminase, GDH, GOT1 and GPT2, seem to all be good strategies to decrease the replenishment of intermediates in the TCA cycle and, consequently, cancer cell proliferation." (PMID 37445598, 2023). "The metabolism of glutamate into α-ketoglutarate is catalyzed by glutamate dehydrogenase 1 (GDH1), glutamate pyruvate transaminase 2 (GPT2), or glutamate oxaloacetate transaminase 1 and 2 (GOT1 (cytoplasmic) and GOT2 (mitochondrial)), which were al previously reported to be overexpressed in cancer." (PMID 35158820, 2022).
infection (8 papers, 2009 to 2025). The state of being infected such as from the introduction of a foreign agent such as serum, vaccine, antigenic substance or organism. "Among these genes, glutaminase 1 (GLS1) and glutamate dehydrogenase 1 (GLUD1) enzyme activity and protein expression were elevated, while glutamic oxaloacetic transaminase (GOT1 and GOT2), glutamate pyruvate transaminase 2 (GPT2), and glutamine synthase (GS) were unchanged during PoRVA infection." (PMID 38905309, 2024). "During the symptomatic phase of CaLam infection, transcripts for 12 genes were differentially expressed: auxin efflux carrier, PP2-B10, RLP7 and Kunitz family protein; CSD2, GPT2, miraculin, NADPH/RbohD, NDR1/HIN1-like 3, PP2-B15, PR6 and starch synthase." (PMID 23586643, 2013). "Post-infection upregulated 20 transcripts in B-48, including G6PD (6 DEGs), GSDH (3 DEGs), GDPGP1 (4 DEGs), GPI (1 DEG), UGDH (1 DEG), UGPUT (3 DEGs), UGGT (1 DEG) and GPT2 (1 DEG)." (PMID 34948367, 2021).
neurodevelopmental disorder (2 papers, 2024). A behavioral and cognitive disorder with onset during the developmental period that involves impaired or aberrant development of intellectual, motor, or social functions. "Previously, we reported autosomal recessive, loss-of-function mutations in the mitochondrial enzyme Glutamate Pyruvate Transaminase 2 (GPT2) that lead to a neurodevelopmental disorder involving cognitive disability." (PMID 39604975, 2024).
GPT2 also shares sentences with these, for which no sentence is quoted: Cirrhosis (2 papers); lung carcinoma (2); non-small cell lung carcinoma (2); renal clear cell carcinoma (2); Spastic paraplegia (2); adenocarcinoma (1); cholestasis (1); craniosynostosis (1); developmental delay (1); developmental disability (1); diffuse large B-cell lymphoma (1); fatty liver disease (1); genetic disorders (1); gestational diabetes (1); Infertility (1); liposarcoma (1); liver fibrosis (1); liver inflammation (1); metabolic disease (1); metabolic syndrome (1); metastatic disease (1); onchocerciasis (1); pancreatic adenocarcinoma (1); parasitic disease (1); pheochromocytoma (1); rheumatoid arthritis (1); sarcoma (1); sarcopenia (1); signet ring cell carcinoma (1); soft tissue sarcoma (1).
A further 2 diseases each share a sentence with GPT2 in 1 paper.